FASN (fatty acid synthase)
Diseases named in the same sentence as FASN in open-access papers (continued):
Sharing a sentence is not in itself a finding about the gene and the disease.
cancer (continued). "Fatty acid synthase (FASN), a key enzyme in fatty acid synthesis, is overexpressed in most human carcinomas, including lung cancer." (PMID 34083687, 2021). "Our study highlights the impact of ACOT8, ACSL5, FASN, HMGBCS2, and SCD1 genes in lipid metabolism along with their distinctive role in cancer initiation and progression." (PMID 32155177, 2020). "Fatty acid synthase (FASN) is a key lipogenic enzyme and is also overexpressed in various human cancers including salivary tumors." (PMID 32103349, 2020). "Additional rationale for the use of these drugs include the basal over-expression of COX-2 and FASN in MCC and prior studies demonstrating inhibition of MUC2 expression/secretion by targeting these two cancer pathways." (PMID 32811515, 2020). "Studies have shown that fatty acid synthase (FAS) overexpression promoted apoptosis and proliferation in cancer cells." (PMID 33319827, 2020). "Consistently, during BC progression, in cancer cells there is an increase of FABP4 and of lipogenic enzymes, like fatty acid synthase (FASN)." (PMID 32850459, 2020). "Inhibition of several enzymes of de novo lipogenesis, such as FASN, and ACC1 and ACC2, has been tested in different cancer models showing their relevance on tumor growth inhibition." (PMID 33194695, 2020). "Consistently, knockdown of Akt in human cancer cells leads to downregulation of ACLY, ACC, and FASN." (PMID 32947972, 2020). "Enzymes that participate in lipogenesis, such as acetyl-CoA carboxylase (ACC), fatty acid synthase (FASN), and acyl-CoA synthetase long chain family member (ACSL), all show a close relationship with cancer and EMT." (PMID 32850862, 2020). "Both FASN mRNA and protein levels have been shown to be overexpressed in most human cancers including PDAC, making FASN an important disease biomarker." (PMID 30728898, 2019). "We analyzed the expression of five major DNFA enzymes SCD, FASN, ACLY, ACSS2 and ACACA using RNA-Seq data from 30 diverse cancer types in The Cancer Genome Atlas (TCGA)." (PMID 31316083, 2019). "It has been shown that co-silencing of FASN and ACSS2 induces cell death in biologically diverse cancer cell lines." (PMID 31092908, 2019). "An upregulation of the enzymes involved in this pathway, such as ACC, FASN and SCD1, has been observed in various types of cancer (breast, prostate...), and their inhibition in cancer cells leads to inhibition of cell proliferation and induction of apoptosis." (PMID 31477154, 2019). "In recent years, fatty acid metabolism has been evaluated as a potential cancer target for treatment, and, according to the results, the inhibition of FASN and ACAT2 leads cancer cells to apoptosis." (PMID 31240215, 2019). "Genes controlling lipogenesis, including SREBP1, FASN, SCD1, and acetyl-CoA carboxylase-1 (ACC1), are frequently upregulated in cancer cells." (PMID 30791926, 2019). "We found that high expression of SCD, FASN and ACACA significantly correlates with poor prognosis in all cancers considered collectively." (PMID 31316083, 2019). "Elevated level of SREBP1, one of the key transcription factors that regulate the transcription of lipogenic enzymes such as FASN and ACLY, has been found in numerous types of cancer." (PMID 31772672, 2019). "The six main genes are involved in the cancer and inflammatory processes (YWHAZ, CCL2 and SMPD2) and lipid droplet formation and metabolism (CIDEC, VLDLR and FASN) and significantly increased in NASH patients compared to control or NAFL groups." (PMID 31717414, 2019). "Cancer cells upregulate monoacylglycerol lipase, acetyl-CoA carboxylase (ACC), and fatty acid synthase (FASN), all which are involved in lipid metabolism." (PMID 30151352, 2018). "Fatty acid synthase (FASN), a key lipogenic enzyme catalyzing the last step in de novo biogenesis of fatty acids, has been studied extensively in various cancers." (PMID 29784041, 2018).
cancer (continued). "FASN expression can be increased, though, in human epithelial cells infected with EBV in its lytic form and in cancer cells." (PMID 29937761, 2018). "In several types of cancer, lipogenesis is increased by overproduction of fatty acid synthase (FASN), the enzyme that converts acetyl CoA and malonyl CoA to fatty acids and acts as an oncogene by promoting cancer cell proliferation and growth." (PMID 29584711, 2018). "SREBP targets such as fatty acid synthase and LDL-receptor are often found to be elevated in cancer cells, thus implicating SREBP in deregulated lipogenesis in cancer cells and targetting lipid supply serves as a potential target for anticancer therapy." (PMID 29934362, 2018). "Our group has studied the reference FASN inhibitors C75 and EGCG in several cancer cell lines, including MDA-MB-231, in which the IC50 values were 46.6 ± 2.2 and 149.0 ± 6.7 μM, respectively." (PMID 29751678, 2018). "Fatty acid synthase (FASN), the key metabolic enzyme of de novo lipogenesis, provides proliferative and metastatic capacity directly to cancer cells have been described." (PMID 30619288, 2018). "We obtained a consistent result from C75, a pharmacologic inhibitor of FASN in the DNL pathway; that inhibition of the DNL pathway promoted apoptosis in cancer cells." (PMID 29928578, 2018). "Key regulators of lipogenesis—SREBPs, acetyl-CoA carboxylase (ACC), fatty acid synthase (FASN), and stearoyl-CoA desaturase 1 (SCD1) —are significantly up-regulated in various human cancers." (PMID 29784041, 2018). "Compared with the control group, cancer cell-derived exosomes were significantly and positively correlated with lipogenesis since the levels of ACLY, FASN and USP2a were increased in exosome-challenged HSCs." (PMID 30591064, 2018). "In the present study, FASN was shown to be upregulated in ACTH-PAs, which was similar to other types of cancer, while enzymes related to fatty acid catabolic metabolism, such as ACADVL, ACADM, and ACAA2, were downregulated in ACTH-PAs." (PMID 30532734, 2018). "(−)-Epigallocatechin 3-gallate (EGCG) is a natural polyphenol from green tea with reported anticancer activity and capacity to inhibit the lipogenic enzyme fatty acid synthase (FASN), which is overexpressed in several human carcinomas." (PMID 29751678, 2018). "Met downregulated expression of enzymes of fatty acid de novo synthesis, such as ATP Citrate Lyase (ACLY), Fatty Acid Synthase (FAS), Fatty Acyl-CoA Elongase 6 (ELOVL6), and Stearoyl-CoA Desaturase-1 (SCD1) in cancer cells." (PMID 28230778, 2017). "Fatty acid synthase (FAS), as a key enzyme involved in de novo lipogenesis, is highly expressed in many cancers." (PMID 28427229, 2017). "Inhibitors of FASN (C75 or TVB-3166) or ACC (ND-646) have been shown to effectively suppress the growth and viability of cancer cells, demonstrating the importance of endogenous FA synthesis in oncology." (PMID 28938608, 2017). "Beside fatty acids uptake, it has been shown that many cancer cells upregulates acetyl-Coa carboxylase (ACC) and fatty acid synthase (FASN) expression to increase de novo lipogenesis and that these high levels correlate with poor prognosis [44•]." (PMID 29188139, 2017). "Inhibiting key enzymes involved in fatty acid synthesis, including FASN, ACC, and ACLY, with small molecules or knockdowns reduces cell proliferation, induces the apoptosis of cancer cells, and decreases the growth of human tumors grown as mouse xenografts." (PMID 28421159, 2017). "Akt/mTORC1 signaling is frequently activated in cancer, and leads to upregulation of sterol regulatory element-binding protein-1c (SREBP-1c), which transcriptionally activates FASN." (PMID 28654693, 2017).
cancer (continued). "Here, we investigated the impact of CCN1 expression on fatty acid synthase (FASN), a metabolic oncogene thought to provide cancer cells with proliferative and survival advantages." (PMID 27713913, 2016). "However, the contribution of FASN to the maintenance of cancer stem cells remains unclear." (PMID 26808816, 2016). "Chemical or RNAi-mediated inhibition of key enzymes involved in fatty acid synthesis, including FASN, ACC and ACLY, reduces cell proliferation, induces apoptosis of cancer cells and retards the growth of human tumors in mouse xenograft models." (PMID 27223259, 2016). "Fatty acid synthase (FASN) is crucial to de novo long-chain fatty acid synthesis, needed to meet cancer cells’ increased demands for membrane, energy, and protein production." (PMID 25947066, 2015). "Inhibition of FASN or palmitoyl acyltransferases reduced the activity and down-regulated the levels of EGFR, and sensitized cancer cells to EGFR tyrosine kinase inhibitors." (PMID 26378037, 2015). "However, it remains unclear whether cancer cells preferentially oxidize exogenously-derived fatty acids or favor the oxidation of endogenous fatty acids, which are synthesized at a high rate by FASN." (PMID 25970773, 2015). "Importantly, activation of fatty acid oxidation and consequent downregulation of stress-response signaling pathways may be key adaptation mechanisms that mediate the effects of FASN on cancer cell survival and metastasis, providing a strong rationale for targeting this pathway in advanced CRC." (PMID 25970773, 2015). "Both major consumers (LDHA, FASN) and producers (GAPDH, MTHFD and MDH2) of NAD(P)H are subject of major research efforts as drug targets against cancer." (PMID 25621879, 2015). "Together, these data indicated that GA prevents lipogenesis of cancer cells via inhibiting lipogenic genes ACC, FASN, and SREBP-1." (PMID 25895130, 2015). "Since both FASN and AMPK have been actively evaluated as targets for cancer therapy in pre-clinical and clinical trials, a better understanding of the interconnection between these proteins is necessary in order to develop more advanced therapeutic strategies." (PMID 25970773, 2015). "By inhibition of glycolysis and fatty acid synthase (FAS), the key enzyme for fatty acid synthesis, we confirmed the deuterium labeled lipids in cancer cells were from de novo lipid synthesis." (PMID 25351207, 2014). "The inhibition of the FASN activity reduces the cancer cells’ proliferative capacity, suggesting that FFA act as an energy source for cancer cells." (PMID 24829560, 2014). "PEMT predictive capacity in addition to LPL and FASN is explicable as FASN and LPL only supply the cancer tissue with long-chain fatty acids, which are then further used as constituents in phospholipid synthesis." (PMID 24932311, 2014). "Inhibition of FASN also enhances accumulation of cofactor nicotinamide adenine dinucleotide phosphate (NADPH) that, therefore, leads it to be transformed into ROS in cancer cells." (PMID 25255125, 2014). "Recent studies have shown that FASN and HER2 are both overexpressed in certain types of cancer cells." (PMID 24778702, 2014). "Fatty acid synthase (FASN), responsible for the de novo synthesis of fatty acids, has been shown to act as an oncogene in various human cancers." (PMID 24979135, 2014). "We have demonstrated that expression of the fatty acid synthase (FASN), which is important in palmitate synthesis and cell proliferation in cancer cells, is potently activated by FBI-1 in the presence of sterol regulatory element binding protein-1 (SREBP-1)." (PMID 23658227, 2013). "PCa related exosomes from clinical samples in general show the presence of some cancer related proteins such as CD9, CD81, and TSG101, Annexin A2, Fatty Acid Synthase (FASN) and a PCa specific biomarker, FOLH1 (Prostate Specific Membrane Antigen or PSMA)." (PMID 24351670, 2013).
cancer (continued). "Fatty acid synthase (FASN) is frequently activated and overexpressed in human cancers, and plays a crucial role in the carcinogenesis of various cancers." (PMID 23725225, 2013). "In this regard, pharmacologic inhibition or knockdown of Fatty Acid Synthase (FASN) and Acetyl-CoA Carboxylase (ACC), key enzymes of lipid synthesis in rapidly proliferating cells, can lead to cancer cell growth arrest and apoptosis." (PMID 23056418, 2012). "The limited experimental evidence available shows that, in cancer cells, a cross-regulation between FASN and HER2 exists, and also that pharmacological blockade of FASN with C75 can overcome acquired resistance to trastuzumab." (PMID 22177475, 2011). "As with FASN and ACC, marked elevation of ACLY expression and activity has been reported in cancer cells." (PMID 19352381, 2009). "To date, no FASN inhibitor has been approved for cancer treatment, toxicity and metabolic side effects remain potential concerns." (PMID 41550490, 2026). "FASN has been considered a promising target for anti-cancer drug discovery due to its up-regulated expression in cancer cells and absence in most normal non-lipogenic tissues." (PMID 41158759, 2026). "Human fatty acid synthase (FASN), the sole cytosolic enzyme responsible for de-novo lipid synthesis in mammalian cells, is essential for cancer cell survival but not for normal cells due to sufficient dietary lipids." (PMID 41158759, 2026). "Consistently, FASN mediated palmitic acid de novo synthesis not only regulates FAO, but also affects protein palmitoylation, however, the crosstalk between the FASN-ACSL-FAO axis and FASN-ACSL-palmitoylation axis and their contributions to cancer remains to be further explored." (PMID 40290117, 2025). "Cancer cells exhibit a heightened reliance on de novo lipogenesis, even in the presence of abundant extracellular lipids, with key enzymes such as ACLY, ACC1, and FASN identified as promising therapeutic targets." (PMID 41291880, 2025). "This was accompanied by the upregulation of key enzymes involved in synthesis (FASN), elongation (ELOVL1,2,5,6,and 7), and desaturation (FADS1 and FADS2) in ovarian tissue compared to NC groups, implicating these pathways in cancer progression." (PMID 40371224, 2025). "Furthermore, siRNA‐mediated depletion of FASN significantly inhibited the proliferation of KAR and BxPC3 cancer cells, as demonstrated by decreased Ki67 staining." (PMID 40621620, 2025). "This contrasts with findings in rat hepatocytes, where resveratrol inhibited fatty acid and triacylglycerol synthesis by reducing acetyl-CoA carboxylase (ACC) activity without affecting FASN, highlighting cancer-specific effects." (PMID 40733158, 2025). "Research should also explore the potential of combining exercise with drugs that target lipid metabolism, such as inhibitors of FASN, ACC, or CD36, to create synergistic effects that might further enhance cancer treatment." (PMID 40487761, 2025). "Studies have demonstrated that fatty acid synthase expression and activity are extremely low in non-malignant adult tissues but significantly increased in certain solid and aggressive cancers." (PMID 41008648, 2025). "We observed a significant upregulation of ACLY, FASN, and SCD1 in primary cancer and CRPC samples." (PMID 39988626, 2025). "Furthermore, AMPK downregulates fatty acid synthase (FAS), thereby reducing lipogenesis, a metabolic process frequently upregulated in cancer." (PMID 40805165, 2025). "This regulation is through suppressing the transcription and activity of SREBP1 target genes, such as FASN and SCD1, which suggests that NR4A1 agonists may potentially be useful in managing SREBP1-driven cancers." (PMID 40427160, 2025).
cancer (continued). "However, the expression of WTAP, YTHDC1 and FASN was increased in NAFLD/NASH/HCC samples, indicating m6A-dependent downregulation of AP-2α during the inflammation-cancer progression." (PMID 40180937, 2025). "FASN, ACACA, ACLY, and ACSL4 are considered key enzymes in lipid metabolism, and previous studies have shown that they can promote the proliferation of various cancers." (PMID 39891099, 2025). "Similarly, enzymes involved in glutamine metabolism (e.g., GLS1, GDH) and lipid biosynthesis (e.g., FASN, ACLY) further underscore the metabolic dependencies that distinguish cancer cells from normal counterparts." (PMID 41154605, 2025). "Inhibiting key enzymes such as fatty acid synthase (FASN) or acetyl-CoA carboxylase (ACLY) can reduce the energy supply of tumor cells, while potentially increasing immune cell attacks on tumors, providing new strategies for cancer treatment." (PMID 39654883, 2024). "In valproic acid (a promising drug for cancer treatment)-treated PC-3 cells, overexpression of C/EBPα could rescue the protein levels of SREBP1, ACC1, FASN, and Bcl-2, resulting in attenuated apoptosis and lipid accumulation." (PMID 38560498, 2024). "Differences in the growth time courses of FASN+ and FASNKO cell populations cannot be explained by the effect of FASN on cell division rates, but rather by the fine-tuning of the interaction between resource availability and metabolic rates of cancer cells." (PMID 39349429, 2024). "Accumulating evidence has shown that multiple lipogenic enzymes, such as FASN, ACC, SCD1, and ACLY, are aberrantly upregulated in a wide variety of cancers, driving FA synthesis and contributing to lipogenesis and the progression of cancer cells." (PMID 38491348, 2024). "RAS is pivotal for macropinocytosis formation, yet it also inhibits lipid peroxidation through multiple pathways such as NFE2L2 and fatty acid synthase (FASN), suggesting that targeting RAS may have varied effects on specific cancer cells." (PMID 38844964, 2024). "Interestingly, overexpression of FASN correlated significantly with a stemness gene signature and poor prognosis in patients with HER2+ GC, highlighting its role in cancer malignancy." (PMID 39624081, 2024). "Rapidly proliferating cancer cells then use the excess acetyl-CoA, via FASN and a second important enzyme, acetyl-CoA carboxylase (ACC), for de novo synthesis of lipids, which are the building blocks of the cell membranes of new cancer cells." (PMID 38611595, 2024). "Interestingly, analysis of the Depmap dataset shows that SCD dependency inversely correlates with the expression levels of both FASN and ACACA (ACC) across all cancer cells lines and particularly AML ones." (PMID 39187579, 2024). "Additionally, a pan-cancer analysis demonstrated dysregulated expression patterns of SIRT6, LRP1, and FASN across multiple tumor types." (PMID 39071712, 2024). "Further analyses indicated that FASN and APP were promising targets for anti-cancer therapy." (PMID 39332525, 2024). "Furthermore, inhibition of FASN and ACACA leads to apoptosis in cancer cells, whereas the addition of exogenous fatty acids restored normal cell growth." (PMID 39457100, 2024). "Notably, CSCs often show a positive correlation between the levels of FASN and ACC expression under specific conditions, and FASN is more vulnerable to attacks in CSCs compared to regular cancer cells." (PMID 38994204, 2024). "FASN inhibitors, such as orlistat or TVB-2640, reduce the availability of lipids needed for membrane synthesis and energy storage, increasing the vulnerability of cancer cells to radiation-induced damage." (PMID 39796683, 2024). "TCGA pan-cancer analyses showed a robust negative correlation between FASN expression and cytolytic activity, HLA-I, and HLA-II immune signatures (PCCs = −0.22, −0.23, −0.26, FDR-adjusted p-values < 10−100)." (PMID 39349429, 2024).